APC (APC regulator of Wnt signaling pathway)
Diseases named in the same sentence as APC in open-access papers (continued):
Sharing a sentence is not in itself a finding about the gene and the disease.
sigmoid colon cancer (1 paper, 2019). A malignant neoplasm involving the sigmoid colon. "Interestingly, the same stop-gain mutation in nucleotide position c.4128T > G (p.Tyr1376Ter) in the APC gene was detected in a patient with sigmoid colon cancer at the age of 17 (Patient ID: CRC616)." (PMID 31428572, 2019).
soft tissue sarcoma (1 paper, 2021). A malignant neoplasm arising from muscle tissue, adipose tissue, blood vessels, fibrous tissue, or other supportive tissues excluding the bones. "APC was found to be lost in a subset (25%) of MPNSTs in the most recent TCGA Research Consortium analysis on soft tissue sarcomas." (PMID 33808166, 2021).
Sotos syndrome (1 paper, 2022). Sotos syndrome is a rare multisystemic genetic disorder characterized by a typical facial appearance, overgrowth of the body in early life with macrocephaly, and mild to severe intellectual disability. "APC caught our intention given the implication of APC2-related member in Sotos syndrome and its role as a negative regulator of the Wnt/β-catenin signaling pathway, which plays a critical role in cutaneous melanoma." (PMID 36230787, 2022).
spindle cell tumor (1 paper, 2026). "MUC4-positive fibroblastoma is a newly characterized fibroblastic neoplasm, typically presenting as a bland spindle cell tumor with diffuse cytoplasmic MUC4 expression, nuclear β‐catenin positivity, and APC gene alterations." (PMID 41773132, 2026).
Splenomegaly (1 paper, 2021). Abnormal increased size of the spleen. "It is known that APC gene mutation causes splenomegaly and can also affect other organs, such as the thymus and liver." (PMID 34063173, 2021).
systemic sclerosis (1 paper, 2015). A chronic disorder, possibly autoimmune, marked by excessive production of collagen which results in hardening and thickening of body tissues. "However, the clinical use of these inhibitors may be limited by the intestinal toxicity in APC-mutant CRC models and local or systemic toxicity in the fibrotic tissue of systemic sclerosis." (PMID 26056602, 2015).
tuberous sclerosis (1 paper, 2021). Hereditary disease characterized by seizures, intellectual disability, developmental delay, and skin and ocular lesions. "Among these, the most frequently mutated genes were TSC2 (22 cases), linked to tuberous sclerosis; APC (16 cases), linked to hereditary colon cancer; and the DNA polymerase POLE (16 cases), involved in predisposition to multiple cancers." (PMID 33809641, 2021).
tumor predisposition syndrome (1 paper, 2024). "Germline mutations of the APC gene are responsible for the development of FAP, a tumor predisposition syndrome." (PMID 39125758, 2024).
uremia (1 paper, 2024). A clinical syndrome associated with the retention of renal waste products or uremic toxins in the blood. "For genes with stable expression in uremia, we overlapped the genes obtained by LASSO and SVM-RFE algorithms to obtain three genes, including ZBTB2, APC, and ERLIN2." (PMID 39328595, 2024).
Usher syndrome (1 paper, 2017). A syndromic diseae characterized by the association of sensorineural deafness (usually congenital) with retinitis pigmentosa and progressive vision loss. "Mutations were found outside of the CDR, including APC (N = 4), FAM170A (N = 2) and GPR98 (N = 2), the latter previously found to be involved in germ line mutation in Usher syndrome." (PMID 28031539, 2017).
yolk sac tumor (1 paper, 2022). A non-seminomatous malignant germ cell tumor composed of primitive germ cells. "Another study focusing on the aberrations of the adenomatous polyposis coli (APC) tumor suppressor in GCT arising during childhood and adolescence discovered methylation of APC and loss of heterozygosity at 5q21-22 in yolk sac tumor and teratomas." (PMID 35723395, 2022).
tumor (1,859 papers, 1993 to 2026). "Tumours in most groups were predominantly monoclonal, as indicated by the presence of one or two APC-truncating mutations or a single Ctnnb1 exon-3 mutation." (PMID 41339549, 2026). "As with the p.I35S mutations in Ctnnb1, this suggests that subsequent loss of Fbxw7 promotes tumour formation by a subset of transformants with existing N-terminal truncations of APC." (PMID 41339549, 2026). "There is evidence that desmoid tumours resulting from the growth of mesenchymal stromal cells in a wound healing setting are associated with deregulated WNT signalling due to APC loss." (PMID 41518037, 2026). "Loss of the APC tumour suppressor is ubiquitous in CRC and is generally perceived as an early event and strong driver of the disease." (PMID 41339549, 2026). "Loss of APC was previously thought to promote tumor progression mainly through deregulated Wnt/β-catenin signaling." (PMID 41486293, 2026). "In a recent study, approximately 30% of unexplained adenomatous polyposis had at least one tumour harbouring the APC c.835-8A>G mutation, suggesting that pks+ E." (PMID 40237887, 2025). "Adenomatous polyposis coli (APC) is a tumor suppressor and gatekeeper gene mutated in more than 80% of people with early-stage sporadic CRC." (PMID 40205952, 2025). "Mutated APC promotes WNT signaling activation favoring tumor regrowth during HH inhibitors treatment following an early response." (PMID 41515948, 2025). "Readthrough of premature stop codons in APC appears as a promising therapeutic strategy for tumours with APC truncating mutations in preclinical studies." (PMID 40237887, 2025). "Recent preclinical models show that PSCC can become resistant to cisplatin when the tumor loses the PTEN tumor suppressor (especially on a SMAD4/APC-deficient background)." (PMID 41514559, 2025). "Using natural language queries, AI-HOPE-WNT investigated co-mutation patterns between AXIN1 and APC by tumor location." (PMID 40860720, 2025). "Classic FAP patients develop 100s to 1000s of premalignant adenomas which demonstrates that APC mutations drive tumor growth in vivo." (PMID 41514557, 2025). "While KRAS mutations activate proliferative signaling pathways, tumor formation appears to require additional genetic alterations such as APC mutations, which disrupt tumor suppressor mechanisms." (PMID 41285904, 2025). "For instance, the loss of function of tumour suppressors such as the adenomatous polyposis coli (APC) is an example of this phenomenon." (PMID 40710347, 2025). "As most adenomatous polyps acquire somatic APC mutations, testing multiple neoplasms is important to differentiate somatic APC mutations from a likely mosaic APC variant." (PMID 40237887, 2025). "A common initiating event is loss-of-function mutation in the tumor suppressor, adenomatous polyposis coli (APC), which leads to disruption of the Wnt signaling pathway and dysregulated cell growth that promotes the formation of intestinal polyps." (PMID 39941740, 2025). "A study introduces an adenomatous polyposis coli (APC) gene mutation into an animal tumor model, which initiates the growth of benign tumors and epigenetic modifications, such as methylation of the p16 gene." (PMID 39836268, 2025). "Most frequently, inactivating mutations of the tumor suppressor APC impair degradation of β‐catenin, resulting in higher β‐catenin‐dependent transcription, and initiating tumor growth." (PMID 39022865, 2025).
tumor (continued). "APC mutations invariably indicate a tumour of colorectal origin but can occur in association with MSH6, which predicts DNA microsatellite instability but does not display such a feature." (PMID 40022227, 2025). "The adenomatous polyposis coli (APC) gene is a canonical tumor suppressor, with loss-of-function mutations present in more than 80% of sporadic colorectal cancers." (PMID 41091816, 2025). "The initial driver mutation often arises in the adenomatous polyposis coli (APC) gene, a critical tumor suppressor, promoting the formation of benign adenomas or polyps." (PMID 40002218, 2025). "The WNT/β‐catenin pathway, in which mutations in APC play a central role, is associated with tumor initiation, maintenance, and poor prognosis." (PMID 40926327, 2025). "A later study detected KRAS mutations in 23% of FAP tumor samples and somatic APC mutations in 69% of the patients." (PMID 41488735, 2025). "APC mutations have been proposed as potential sources of tumor-specific neoantigens for cancer vaccine development." (PMID 40429703, 2025). "These cells transformed into tumor-initiating cells under the sustained activation of the Wnt/β-catenin signaling pathway mediated by APC gene mutations." (PMID 41346579, 2025). "Her lab previously identified USP7, a deubiquitinating enzyme, as a novel tumor-specific Wnt target in APC-mutated CRC, affecting over 80% of cases." (PMID 41221269, 2025). "The tumour suppressor APC is part of the destruction complex that regulates β-catenin, and in CRCs, APC inactivating mutations are almost always mutually exclusive with CTNNB1 activating mutations." (PMID 40389436, 2025). "Mechanistic studies using lineage tracing and genetic models have demonstrated that Paneth-like cells can act as cells of origin for intestinal tumors, particularly in the context of inflammation and loss of tumor suppressors such as APC." (PMID 41002393, 2025). "For instance, varying levels of WNT activity are observed within a single CRC despite all tumor cells carrying an identical driver mutation in APC." (PMID 39472498, 2025). "This study examined the impact of inflammation and genetic mutations on tumor development in a mouse model harboring APC, KRAS, or combined APC; KRAS mutations." (PMID 41285904, 2025). "Approximately 70% of both sporadic and hereditary CRC cases harbor deletions or mutations in the APC gene, underscoring its central role in tumor initiation." (PMID 40943055, 2025). "For example, genetic manipulation of DEFA3, MMP11, or MYL9 in APC Min/+ mice would directly reveal their causal roles in tumor initiation, progression, or metastasis." (PMID 41009818, 2025). "In the context of CRC, deletion of a single JAG1 allele in an APC mutant background significantly reduces tumor burden, which is associated with decreased levels of active Notch1." (PMID 41294868, 2025). "When APC is mutated, β-catenin dissociates from APC, activating the expression of oncogenes like c-myc and cyclin D1, thereby promoting tumor cell growth." (PMID 40641920, 2025).
tumor (continued). "In this study, frequent tumor formation in APC-mutant mice indicates that APC mutation is a critical early event in tumorigenesis." (PMID 41285904, 2025). "A prime example comes from fruit fly research, which confirmed that in an APC-deficient context, Ras signaling is essential for both tumor initiation and progression, operating in a parallel relationship with the Wnt pathway." (PMID 41303362, 2025). "The authors indicated that STP1002 revealed anti-tumor activity by stabilizing Axins and antagonizing the Wnt/β-catenin pathway in a subset of APC-mutated CRC cell lines." (PMID 40943055, 2025). "FAP-related AF is linked to APC gene deletion and impaired phosphorylation of β-catenin, resulting in aberrant tumor cell proliferation." (PMID 40727479, 2025). "Mutations in tumor suppressors, such as APC, Axin1/2, and RNF43, as well as β-catenin mutations, are common in many cancers." (PMID 40943055, 2025). "In APCMin/+ mice, APC mutation leads to the accumulation of β-catenin in the nucleus, thereby activating tumor-related transcription factors." (PMID 40740230, 2025). "A review of studies analysing APC hypermethylation highlighted APC as a prognostic biomarker associated with advanced tumour stage (Ref." (PMID 40524349, 2025). "A previous study using ApcMin/+ mice reported that DSS administration caused the loss of the wild-type APC allele, which subsequently promoted tumor formation." (PMID 41285904, 2025). "Particularly, the ApcMin/+ (Multiple Intestinal Neoplasia) mouse model has provided valuable insights into the pathogenesis of CRC, the role of APC in tumor suppression, and the underlying mechanisms of polyp formation." (PMID 39594797, 2024). "The patient’s tumor was found to contain somatic mutations in APC (p.Q1549*), APC (p.R904fs), SMAD4 (p.R135*), SMAD4 (p.A190fs), ATR (p.F134fs) and KRAS (p.G12D)." (PMID 38243056, 2024). "In the RRGS-Low subgroup, the higher mutation rate of the APC gene is often associated with reduced tumor aggressiveness and a more favorable prognosis." (PMID 39668832, 2024). "The loss of APC mutations, which are known to disrupt tumor-suppressive pathways and promote aberrant Wnt signaling, suggests a reduction in immune evasion mechanisms." (PMID 39796090, 2024). "This mutation causes functional inactivation of the tumor suppressor activity of the adenomatous polyposis coli (APC) gene." (PMID 38576527, 2024). "The mutations in the Adenomatous Polyposis (APC) tumor suppressor gene are prevalent in colorectal tumorigenesis and lead to the activation of the canonical Wnt signaling network." (PMID 39594797, 2024). "Since at least one allele of APC is mutated in 80% of sporadic colorectal cancers in humans, the ApcMin/+ mouse is a relevant model for studying intestinal tumorigenesis and tumor growth." (PMID 38732562, 2024). "The adenomatous polyposis coli (APC) gene, a well-known tumor suppressor, is a component of protein complexes, and somatic APC mutations are found in more than 80% of sporadic CRC." (PMID 39587482, 2024). "Similar to the findings in the right side vs. left side comparison, the APC gene showed similar mutation frequencies in the three tumor locations." (PMID 38409377, 2024). "Loss of additional tumor suppressors including LKB1 or APC increased the rate of tumor progression, altered the evolutionary trajectories, and increased fitness of some subclones." (PMID 37832945, 2024). "Its loss ameliorates tumour growth abrogate the super competitor phenotype of APC and initiates the differentiation of tumours." (PMID 39443725, 2024).
tumor (continued). "The APC gene, a tumor suppressor in CRC, with somatic mutations in 80% of sporadic CRC presents adenomatous polyposis coli (APC) at an early stage of colorectal tumors." (PMID 38542332, 2024). "In this case, a frameshift deletion occurred in the APC gene on chromosome 5, which encodes a tumor suppressor protein that acts as an antagonist of the Wnt signaling pathway and is also involved in other processes, including cell migration and adhesion." (PMID 38730456, 2024). "A mutation in the adenomatous polyposis coli (APC) tumor-suppressor gene, which leads to a loss of cellular adhesion and an increase in cellular proliferation, leads to the formation of polyps." (PMID 38827000, 2024). "Specifically, in cases where APC mutations were detected, β-catenin showed a distinct localization within the nucleus or cytoplasm of the tumor cells." (PMID 38414697, 2024). "Fatty acid oxidation is a metabolic pathway utilized by tumor cells that is crucial for malignant progression; however, its association with APC/C remains to be explored." (PMID 38783346, 2024). "In this study, we investigated the possibility to control the abundance of β-Catenin protein via DUBs that are relevant to CRC that is driven by loss of the tumour suppressor APC." (PMID 39443725, 2024). "In the case of colorectal cancer (CRC), though a significant percentage of patients have KRAS mutations, the primary initiating event of neoplasm is mediated by either the loss of function of APC or mutation of β-catenin." (PMID 39056802, 2024). "During ICI treatment in PR patients, BRAF and APC mutations shifted as the tumor responded to or resisted treatment." (PMID 39796090, 2024). "APC is a tumor suppressor gene that encodes a protein responsible for β-catenin degradation, a key regulator of gene transcription that controls cell proliferation and differentiation." (PMID 39684219, 2024). "Different truncations or mutations of APC lead to specific tumor types throughout the body in a Wnt/β-catenin dosage-dependent manner." (PMID 39320349, 2024). "For example, some reports showed a high concordance (77%) of KRAS variant between tumor tissues and plasma, and concordance between tissue and blood ctDNA ranged from 63.2% (APC) to 85.5% (BRAF) in CRC." (PMID 38777950, 2024). "In total, 13 of 97 patients (13%) carried a germline (likely) pathogenic variant in a well-known tumor predisposition gene: APC (n = 1), BRCA2 (n = 2), CHEK2 (n = 4), DICER1 (n = 4), HOXB13 (n = 1), and MITF (n = 1)." (PMID 38415346, 2024). "In total, 13 patients (13%) carried a P/LP variant in a known autosomal dominant tumor predisposition gene: APC (n = 1), BRCA2 (n = 2), CHEK2 (n = 4), DICER1 (n = 4), HOXB13 (n = 1), and MITF (n = 1)." (PMID 38415346, 2024). "In patients with a high tumor mutational burden, other significantly mutated genes were APC (p = 0.029), and ARID2 (p = 0.029)." (PMID 39028418, 2024). "Actomyosin-mediated cell mechanics regulate tumor cell self-renewal through cytoskeleton/APC/Wnt/β-catenin-Oct4 signaling, which is relevant in the clinical samples and associated with tumor differentiation and patient survival." (PMID 37746658, 2023). "In conclusion, our data provide robust in vivo evidence of USP7 as a tumor-specific therapeutic target in APC-mutated CRCs." (PMID 36669491, 2023).